APOE (apolipoprotein E)
Diseases named in the same sentence as APOE in open-access papers (continued):
Sharing a sentence is not in itself a finding about the gene and the disease.
atherosclerosis (continued). "Adiponectin levels were found not to correlate with a suppression of the atherosclerosis process in mice using adiponectin deficient and overexpressing mice crossed with either low-density lipoprotein receptor or ApoE deficient mice." (PMID 24324556, 2013). "In addition to promoting formation of aortic aneurysms, many studies have reported that chronic subcutaneous infusion of AngII into mice augments development of atherosclerosis in both apoE -/- and LDL receptor -/- mice." (PMID 24244746, 2013). "Therefore, the ability of TTA to inhibit the development of atherosclerosis in apoE-/- mice fed on a high-fat diet was investigated." (PMID 24324736, 2013). "Other studies have also investigated the role of GzmB and Prf1 in atherosclerosis.One study by Viswanathanet al showed that GzmB/ApoE DKO mice exhibit a trend towards reduced plaque development compared to ApoE KO mice in a model of aortic allograft vasculopathy." (PMID 24205352, 2013). "ApoE KO mice spontaneously develop atherosclerosis even when fed a normolipidemic diet." (PMID 23710353, 2013). "Here we determined in APOE knockout mice the impact of total removal of adrenal function through adrenalectomy (ADX) on two inflammation-associated pathologies, endotoxemia and atherosclerosis." (PMID 24265824, 2013). "Here we show that AT1R blockade using a pharmacological approach and AT1R deficiency by gene deletion attenuates atherosclerosis and improves endothelial function in diabetic and non-diabetic ApoE−/−-mice." (PMID 23374104, 2013). "In the LDL-R−/− model, we studied the effect of Dunaliella on early atherogenesis; therefore, in the present study we aimed to investigate the effect of Dunaliella on the progression of established atherosclerosis, using apoE−/− mouse model characterized with advanced atherosclerotic lesions." (PMID 24175283, 2013). "To determine whether the BAFFR antibody prevents atherosclerosis development, we treated ApoE−/− mice with the antibody while feeding them a high fat diet (HFD) for 8 weeks." (PMID 23560095, 2013). "Although results of these studies provided important insights into the role of macrophage-derived apoE in both plasma cholesterol homeostasis and atherosclerosis, most were conducted in irradiated Apoe−/− mice using either transfected or transgenic inter-species expression of human apoE." (PMID 22606237, 2012). "As shown in eNOS over-expressing apoE−/− mice, increased superoxide generation by uncoupled eNOS may accelerate atherosclerosis." (PMID 22291917, 2012). "Therefore, increased atherosclerosis development in apoE−/−/eNOS−/− animals is likely due to local changes like increased endothelial activation and L/E- interactions reported here." (PMID 22291917, 2012). "The ApoE-gene-knockout mice mouse is a suitable animal model for study of atherosclerosis." (PMID 22811752, 2012). "In humans, ApoE deficiency, or the presence of mutant forms of ApoE, results in type III hyperlipidemia characterized by the presence of elevated VLDL lipoproteins and early age onset of atherosclerosis." (PMID 23029000, 2012). "In apoE−/− atherosclerosis, L/E-interactions are increased, compared to C57BL/6J controls." (PMID 22291917, 2012). "Consistent with a role for C5a in atherosclerosis, inhibition of C5aR with antagonist or blocking monoclonal antibody for 7 days after wire-induced endothelial injury in apoE−/− mice reduced neointimal thickening, monocyte/macrophage and neutrophil infiltration, and expression of VCAM-1 and PAI-1." (PMID 24278688, 2012). "In contrast to these protective effects, iNOS produces high concentrations of NO, which serves important roles in host defence against tumor cells and pathogens, but also contributes to tissue damage in chronic inflammation and increases apoE−/− atherosclerosis." (PMID 22291917, 2012).
atherosclerosis (continued). "To evaluate whether ginkgolide B influences atherosclerosis, we first observed the characteristics of the aorta surface in ApoE−/− mice with 8 weeks of treatment using a scanning electron microscope." (PMID 22662117, 2012). "Interestingly, blockade of IL-1 signaling by treatment with IL-1R antagonists or genetic ablation of IL-1R results in marked resistance to the development of atherosclerosis in the APOE model." (PMID 23087690, 2012). "However, targeted deletion of the gene for Apolipoprotein E (ApoE knockout mice) leads to severe hypercholesterolemia and spontaneous atherosclerosis." (PMID 23193398, 2012). "Since its creation two decades ago, the apoE-/- mouse, which spontaneously develops hypercholesterolemia and vascular atherosclerotic lesions on a regular chow diet, has greatly contributed to the understanding of the atherosclerosis disease process." (PMID 22330242, 2012). "In contrast, strain 33277, which is closely related to strain 381 does not accelerate atherosclerosis in ApoE deficient mice." (PMID 23300720, 2012). "To address the question of whether loss of GDF‐15 affects the development and progression of atherosclerosis in vivo, we investigated sections of the aortic arch in GDF‐15−/−/apoE−/− and GDF‐15+/+/apoE−/− mice." (PMID 23316317, 2012). "Interestingly, in an ApoE mouse model of atherosclerosis fed on a high-fat diet, PARP inhibition improved endothelial function." (PMID 23443128, 2012). "In this respect, the fact that not only acquired but also connate mtDNA mutations predispose to cardiovascular disease already points to mtDNA damage occurring at an early stage of atherosclerosis, which is further supported by investigations in apolipoprotein E knockout (apoE−/−) mice." (PMID 22382745, 2012). "The authors also speculated that ApoE might use this pathway to deliver self-lipid antigens and exacerbate atherosclerosis, although such removal of antigenic lipids might also be atheroprotective." (PMID 22645694, 2012). "APOE genotypes directly influence lipid metabolism and atherosclerosis." (PMID 22482072, 2012). "Lack of apolipoprotein E (apoE) gene has been clearly demonstrated as a leading cause of severe hyperlipidemia and spontaneous development of atherosclerosis in mammals." (PMID 22520940, 2012). "On the other hand, intranasal immunization of apoE(-/-) mice with a p210-CTB fusion protein preparation reduced atherosclerosis by 35% with increased IgG titers against p210 and CD4+ T regulatory cells without further elucidation of the role of either immune response." (PMID 22347402, 2012). "Here, we examined the development of atherosclerosis in BAFF-R deficient ApoE−/− mice because B2 cells but not B1a cells are selectively depleted in BAFF-R deficient mice." (PMID 22238605, 2012). "This suggests that the dramatically increased atherosclerosis in apoE−/−/eNOS−/−, compared to apoE−/−, is not caused by increased platelet adhesion and subsequent events." (PMID 22291917, 2012). "Concluding, this bioinformatic analysis of ApoE knockout mice revealed critical altered cellular mechanisms governing atherosclerosis and indicated important molecular players that could be important targets for treatment of this complex disease." (PMID 23193398, 2012). "Moreover, mice with combined PON1/apoE KO exhibited more atherosclerosis than apoE KO mice and their LDL particles were more susceptible to oxidation." (PMID 22824324, 2012). "In this view our results emphasize the importance for further investigating the impact of targeting hepatic LRP1 function in the apoE-mediated catabolism of TRL remnants in relation to postprandial dyslipidemia and the other risk factors affecting atherosclerosis development." (PMID 22701627, 2012).
atherosclerosis (continued). "In order to be able to make inferences between the strain specific atherogenic potential of P. gingivalis, we limited our study to strains that have already been evaluated in the same atherosclerosis model (the ApoE null mouse) using similar experimental conditions." (PMID 23300720, 2012). "To address these issues, we performed a systematic analysis of the expression pattern of all three mammalian tribbles in the ApoE−/− fat-fed model of atherosclerosis and show that these proteins are present in smooth muscle cells, endothelial cells and plaque resident macrophages." (PMID 24832046, 2012). "Apolipoprotein E (ApoE) is a 34-kDa circulating glycoprotein, secreted by the liver and macrophages with pleiotropic antiatherogenic functions and hence a candidate to treat hypercholesterolaemia and atherosclerosis." (PMID 22645694, 2012). "Furthermore, deficiency of CD59, the primary inhibitor of C5b-9 formation, in apoE−/− mice resulted in enhanced C5b-9 formation leading to endothelial dysfunction, accelerated atherosclerosis, formation of vulnerable plaques, and premature death." (PMID 24278688, 2012). "Therefore we performed a more detailed study of effect of VKA on plaque calcification in an established model of atherosclerosis, the apoE−/− mice." (PMID 22952653, 2012). "A number of animal studies have also provided compelling evidence that cytomegalovirus plays an important role in the pathophysiology of atherosclerosis, including several studies that have demonstrated more severe atherosclerosis in apoE −/− mice following systemic MCMV infection." (PMID 22570607, 2012). "The mechanisms and progression of atherosclerosis in the apoE-/- mice have been described before." (PMID 22330242, 2012). "The ApoE−/− mouse on a Western diet is a well-established model of atherosclerosis." (PMID 22709928, 2012). "In accordance with recent studies in our lab exploring the role of the A2bAR in the context of atherosclerosis and lipid metabolism on an ApoE null background, we determined here that the A2bAR on normal ApoE background also regulates hepatic SREBP-1 as well as plasma lipids post HFD challenge." (PMID 22848385, 2012). "Betaine therapy also attenuates atherosclerosis in the apoE knockout mouse." (PMID 21747945, 2011). "To analyze the impact of atherosclerosis on heart function, we used aged ApoE-/- mice." (PMID 21711241, 2011). "In this study, we used a well documented, humanized mouse model of atherosclerosis, the ApoE*3Leiden mouse, to provide evidence that alternating high cholesterol (HC) -cholesterol-free (CON) diet can effectively diminish cardiovascular risk factors as compared with daily HC diet." (PMID 21483792, 2011). "The involvement of apoE in Alzheimer's disease, atherosclerosis, and immune responses is well documented, and this novel information can help gain insight towards understanding the mechanistic role of glycosylated apoE residues in these diseases." (PMID 22312457, 2011). "Although rapamycin treatment can protect against atherosclerosis in carotid arteries, studies from our laboratory show that this agent does not affect vascular responsiveness in the resistance mesenteric arteries of apoE-/- mice." (PMID 22082357, 2011). "Results presented here suggest that in atherosclerosis-prone ApoE-/- mice the protective effects of aerobic exercise over an extended period may be significantly diminished by diet and pre-elevated levels of atherogenic lipids." (PMID 21359188, 2011). "Indeed, atherosclerosis in apoE-/- mice was reduced and the endothelial dysfunction of aortic rings was attenuated following ovariectomy and was aggravated by treatment with 17-β-estradiol at doses that were near physiological levels." (PMID 22082357, 2011).
atherosclerosis (continued). "Using atherosclerosis-prone ApoE-null mice we sought to determine whether the benefits of exercise for arterial disease are dependent on the food source of the additional calories." (PMID 21359188, 2011). "Apolipoprotein E (apoE), a 34-kD glycoprotein produced mainly by hepatocytes and also secreted from several cells including macrophages and adipocytes, plays a crucial role in lipoprotein metabolism and atherosclerosis." (PMID 21819577, 2011). "ApoE knockout mice deficient in SR-A or CD36 have been reported to have similar levels of atherosclerosis to wild-type apoE knockout mice, whereas other studies have demonstrated that deletion of these receptors decreases atherosclerosis." (PMID 21904540, 2011). "We then investigated the possible mechanisms by which MNCs could locally mediate the attenuation of atherosclerosis in apoE KO mice." (PMID 21896159, 2011). "MNC therapy attenuates the progression of atherosclerosis in the aortas of apoE KO mice." (PMID 21896159, 2011). "In addition to fat synthesizing enzymes, ranolazine also normalized the expression and protein levels of the fat oxidizing enzyme, Ucp1, in failing hearts of B6 mice with chronic pressure overload and ApoE-/- mice with advanced atherosclerosis." (PMID 21711241, 2011). "The ApoE model of atherosclerosis used in this study is well established." (PMID 21586133, 2011). "Furthermore, adenoviral gene transfer of ETC-642 has been shown to decrease atherosclerosis in apoE-/- mice." (PMID 22128776, 2011). "Hence, the apoE-/- mouse, in addition to being a model for human atherosclerosis, appears to be a suitable experimental model for studying the detrimental effects of 17-β-estradiol on endothelial dysfunction." (PMID 22082357, 2011). "ApoE−/− mice show increased levels of serum total cholesterol and triglycerides compared to wild-type littermates that are further increased when animals receive a high-fat diet and develop severe atherosclerosis." (PMID 21701687, 2011). "Deletion of LRP1 within macrophages has been shown to enhance the extent of atherosclerosis in LDL receptor/apoE double knockout mice and in LDL receptor knockout mice receiving a bone marrow transplant from mice in which LRP1 was selectively deleted in macrophages." (PMID 22174911, 2011). "In addition, endothelial p38α deficiency did not affect the expression of a number of proinflammatory mediators known to regulate atherosclerosis in aortic lesions from ApoE−/− mice fed with HCD for 10 weeks." (PMID 21695272, 2011). "Our results clearly demonstrate that long-term exposure to inhaled nano-NH can induce oxidative stress and inflammation, not only in the lung but also in the cardiovascular system, and that this stress and inflammation can ultimately contribute to progression of atherosclerosis in ApoE−/− mice." (PMID 20864429, 2011). "Deficiency of FABP4 protected against atherosclerosis in apolipoprotein E- (ApoE-) deficient mice with or without high-cholesterol-containing western diets." (PMID 22121495, 2011). "Ranolazine also improved the cardiac function of aged ApoE-/- mice with severe atherosclerosis." (PMID 21711241, 2011). "Previous studies have shown that fine particulate air pollution inhalation leads to insulin resistance, oxidative stress, alteration of vasomotor tone, vascular and visceral inflammation, adiposity, and atherosclerosis in apolipoprotein E knockout (ApoE-/-) mice and other several mouse models." (PMID 21745393, 2011).
atherosclerosis (continued). "In view of these findings, the apoE-/- mouse model allows the investigation of the detrimental effects of 17-β-estradiol on atherosclerosis and contributes to clinical studies that reveal the unfavorable effects of hormone replacement therapy in postmenopausal women." (PMID 22082357, 2011). "Moreover, A recent study has shown that an increase in ILK expression coincides with higher rate of SMC migration within the atherosclerotic plaque in ApoE -/- mice, a reliable model that mimics the progression of atherosclerosis in humans." (PMID 20178627, 2010). "The administration of a recombinant soluble form of RAGE (sRAGE) consisting of its extracellular ligand-binding domain has recently been shown to not only suppress the development of atherosclerosis but also to stabilize established atherosclerosis in diabetic apolipoprotein E-null mice." (PMID 20652047, 2010). "Having demonstrated that diabetic mice express lower A20 levels under inflammatory conditions, we questioned whether restoring A20 levels in the vasculature could prevent accelerated atherosclerosis in diabetic ApoE-null mice." (PMID 21151899, 2010). "This contention results from the aggregate evaluation of the fact that FXR gene ablation results in a pro-atherogenic lipoproteins profile and FXR and ApoE double knockout male mice fed an high fat diet develop an accelerated atherosclerosis in comparison to ApoE−/− single knock out mice." (PMID 20949026, 2010). "Mice deficient in the LDL receptor ligand, ApoE (ApoE−/−) involved in uptake of LDL, fed a HFHC diet, exhibit an atherosclerosis phenotype with high blood oxLDL levels; along the lines of the concept presented herein, these animals also exhibit laminar deposits in BM, as seen in AMD." (PMID 21098885, 2010). "Therefore, we examined the effects of ASA and NCX 4016 on the development of radiation-induced atherosclerosis and compared this with age-related atherosclerosis in ApoE−/− mice." (PMID 20877628, 2010). "Finally, prolonged treatment with T-0681 reduced the development of atherosclerosis by 60% in apoE KOs on Western type diet." (PMID 20090943, 2010). "Double-knockout mice lacking PTX3 and apolipoprotein E (ApoE) in combination with an atherogenic diet are susceptible for atherosclerosis." (PMID 20920344, 2010). "We used the ApoE-/- mice, which are prone to develop atherosclerosis, to understand the molecular mechanism of pulmonary phenotype in response to CS exposure, as well as to study the concept of accelerated decline in lung function and aging in cardiopulmonary comorbid conditions." (PMID 20663150, 2010). "Importantly, another study byZhang and colleagues demonstrate that endothelial specific over-expression ofSIRT1 decreases atherosclerosis in ApoE-/-mice." (PMID 20606250, 2010). "Exposure to UFP promoted atherosclerosis via systemic oxidative stress in ApoE-null mice." (PMID 20307321, 2010). "This may account for the dramatic atheroprotection provided by A20 in the diabetic ApoE-null mouse model via down-regulation of hyperglycemia-dependent and hyperglycemia-independent effectors of atherosclerosis." (PMID 21151899, 2010). "Diabetes accelerates and aggravates atherosclerosis in ApoE-null mice." (PMID 21151899, 2010). "Apolipoprotein (ApoE)−/− mice fed a high-fat diet were used as a model of atherosclerosis." (PMID 19823587, 2009). "Additional evidence for its role in atherosclerosis comes from an animal model showing that in apoE-deficient mice a lack of IL-1β is associated with decreased severity of atherosclerosis." (PMID 19347053, 2009). "Both PDZK1/apoE dKO and apoE KO mice showed significant amounts of atherosclerosis." (PMID 19956623, 2009).